KLF5 (KLF transcription factor 5)
Diseases named in the same sentence as KLF5 in open-access papers (continued):
Sharing a sentence is not in itself a finding about the gene and the disease.
pancreatic cancer (continued). "Since KLF5 and TCF7L2 have been shown to be upregulated in pancreatic cancer stem cells, it would be interesting to validate if GALNT3 and B3GNT3 are driven by any of these TFs." (PMID 34367349, 2021). "Mechanistically, KLF5 promoted expression of E2F1, cyclin D1 and Rad51, while inhibiting expression of p16 in pancreatic cancer cells." (PMID 31327760, 2019). "Furthermore, the downregulation of KLF5 expression promotes the DNA damage induced by olaparib and significantly reduces the IC50 of the RARP inhibitor in pancreatic cancer cells." (PMID 38433576, 2024). "In addition, this study demonstrated the role of abnormal pathways such as Wnt and Notch in pancreatic cancer and identified new genes such as EGLN3, MMP9, and FOS KLF5 and other transcription factors involved in carcinogenesis." (PMID 36052088, 2022). "In the absence of SMAD4, KLF5 cooperates with SOX4 to promote tumor progression in pancreatic cancer cells." (PMID 31822964, 2020). "In other words, analysis of overall survival does not totally reflect KLF5’s key role in determining the prognosis of pancreatic cancer patients." (PMID 31327760, 2019). "Thus, the combination of activation of the KLF5/ZEB1/HMOX1 axis and oxaliplatin may provide a potential therapeutic strategy for pancreatic cancer." (PMID 39827156, 2025). "However, at first, this pathway seemed to not be responsible for KLF5 induction in pancreatic cancer." (PMID 37239940, 2023). "Our screen has uncovered novel pancreatic cancer genes and pathways, most notably highlighting potential roles of a putative NUP153-FAST1 SMAD shuttling axis controlling TGFβ signaling and an oncogenic function of the KLF5 transcription factor, both meriting further study." (PMID 24041470, 2013).
atherosclerosis (27 papers, 2011 to 2025). A disease characterized by the build-up of fatty material and calcium deposition in the arterial wall resulting in partial or complete occlusion of the arterial lumen. "KLF5 contributes to the phenotypic switch of smooth muscle cells from a contractile to a synthetic phenotype, which is associated with the development of atherosclerosis." (PMID 36984888, 2023). "In endothelial cells, KLF5 has been shown to play a pathogenic role in the development of atherosclerosis." (PMID 36984888, 2023). "In the murine model of atherosclerosis, KLF-5 expression is elevated, which is associated with atherosclerosis progression supporting the role of KLF-5 in promoting vascular diseases." (PMID 34502172, 2021). "In summary, KLF14 exerts multi-target protective effects in atherosclerosis, while its antagonistic effects with family members such as KLF5 reveal the complexity and therapeutic potential of the KLF network regulation." (PMID 41373858, 2025). "As well, circUSP9X/miR-148b-3p/KLF5 and circ_USP36/miR-182-5p/KLF5 axes stimulate atherosclerosis similarly." (PMID 41373858, 2025). "Regarding therapeutic potential, KLF5 inhibition has been proposed as a strategy for treating atherosclerosis." (PMID 38725857, 2024). "Studies have suggested that blocking miR-410 promotes HDAC1 expression, increases KLF5-mediated IKBα expression, and inhibits the NF-κB pathway, thereby inhibiting the development of atherosclerosis." (PMID 37405052, 2023). "Overexpression of KLF5 in endothelial cells contributes to endothelial dysfunction, oxidative stress, and inflammation, which are key hallmarks of atherosclerosis." (PMID 36984888, 2023). "The relationship between KLF5 and miRNA-576 also plays an important role in the pathogenesis of atherosclerosis and contributes to disease progression." (PMID 36984888, 2023). "According to previous studies, Krüppel-like factor 5 (KLF5) induces atherosclerosis by promoting VSMC proliferation and migration." (PMID 35055187, 2022). "miR-152 decelerates the progression of atherosclerosis through inhibiting the secretion of inflammatory factors from macrophages by downregulating KLF5." (PMID 33493334, 2021). "The expression of KLF5 is also elevated in aortas of patients with thoracic aortic dissection and atherosclerosis." (PMID 33493334, 2021). "The level of LINC00346 was found to be negatively correlated with Krüppel-like factor 5 (KLF5) expression in atherosclerosis." (PMID 35096842, 2021). "LINC00346 was found to affect the initiation and development of atherosclerosis by regulating the KLF5/LINC00346/miR-148a-3p pathway." (PMID 35096842, 2021). "KLF5 exerts considerable effects on cardiovascular diseases, such as atherosclerosis, cardiac hypertrophy, hypertension, and restenosis." (PMID 33493334, 2021). "Consistent with this, gene and protein expressions of KLF5, a miR‐145 target, were significantly increased in atherosclerosis (P < 0.05 for both CN and VL patients versus both CR and AR patients for both protein and mRNA expression)." (PMID 26992033, 2016). "A considerable body of evidence indicates the pivotal role of KLF5 in cell proliferation, and inhibition of KLF5 expression has been demonstrated recently to inhibit neointima formation, atherosclerosis and hypertension related vascular remodeling." (PMID 25874449, 2015). "Recent studies have demonstrated the implication of KLF5 in tissue remodeling in cardiovascular diseases, such as atherosclerosis, restenosis, and cardiac hypertrophy." (PMID 21951574, 2011). "Therefore, factors like KLF5 and miR-155 exemplify how a molecular pathway can have dual relevance contributing to atherosclerosis in the vasculature and to inflammation-related infertility in the reproductive system." (PMID 41378097, 2025).
atherosclerosis (continued). "When endothelial cells were exposed to exosomes from KLF5-overexpressing VSMCs, they exhibited reduced proliferation, increased permeability, and decreased tight junction proteins changes that mirror endothelial dysfunction in atherosclerosis." (PMID 41378097, 2025). "Similarly, miRNAs such as miR-576, miR-145, and miR-10b-3p attenuate atherosclerosis by directly downregulating KLF5." (PMID 41373858, 2025). "To further elucidate whether KLF5 responds to increased IFSS after atherosclerosis initiation, we applied 3 dyn/cm2 shear stress on VSMCs and examined the expression change of KLF5." (PMID 38725857, 2024). "The anti-atherosclerotic effect of HDAC1 may be related to the miR-410/HDAC1/KLF5/IKBα/NF-κB axis, with miR-410 playing a potential role in the pathogenesis of atherosclerosis." (PMID 37405052, 2023). "Interestingly, the adverse role of KLF5 has also been shown in atherosclerosis as a part of oxLDL–KLF5–miR-29a–F-box and WD repeat domain containing 7 (FBW7) positive feedback loop." (PMID 35991314, 2022). "Since miR-155 acts as an atherosclerosis inducer, regulation of KLF2 and/or KLF5 expression in the vascular system may be important to prevent atherosclerosis." (PMID 35055187, 2022). "VSMCs from patients with atherosclerosis exhibit a significant upregulation of KLF5." (PMID 33493334, 2021). "MiR‐152 targeted KLF5 and suppressed the inflammatory responses in atherosclerosis model." (PMID 33523554, 2021). "Additionally, smooth muscle enriched long noncoding RNA competitively bound to miR‐10b‐3p and exerted an inhibitory effect on miR‐10b‐3p‐KLF5 pathway in atherosclerosis model." (PMID 33523554, 2021). "The expression of other atherogenic biomarkers such as Timp1, Mmp9, Cxcl16, and Klf5 was also similar between groups, as analyzed by real-time PCR, indicating a different mechanism operating in the MG-induced reduction of atherosclerosis development in Apoe−/− mice." (PMID 30959963, 2019). "In this study, we used cultured cells from non‐defected areas of the aorta in patients with atherosclerosis to indirectly show that miR‐145 modulates the phenotypic switch of VSMCs from a contractile to a proliferative state via KLF5 and MYOCD in atherosclerosis." (PMID 26992033, 2016). "miR‐145 may modulate the phenotype of VSMCs via KLF5 to promote the deleterious VSMC proliferative characteristic of atherosclerosis." (PMID 26992033, 2016). "Klf5 expression is strongly induced in activated VSMCs in atherosclerosis." (PMID 25205373, 2014). "Therefore, KLF2 and KLF5 could be considered as new therapeutic targets for atherosclerosis." (PMID 35055187, 2022). "Unlike KLF2 and KLF4, KLF5 aggravates atherosclerosis via non-coding RNAs networks, including miRNAs, lncRNAs, and circRNAs." (PMID 41373858, 2025). "Upregulation of KLF5 significantly increases the expression of interleukin-1 (IL-1), IL-6, TNF-α, and CD38, accelerating the activation and infiltration of macrophages, leading to the pathogenesis of atherosclerosis and intracranial aneurysms." (PMID 33493334, 2021). "Combined, targeted hypermethylation of either the KLF5 mRNA or miR-29a might prove therapeutic in conditions where VSMC hyperproliferation holds a central pathophysiologic role, including atherosclerosis, arterial aneurysms, and both pulmonary and systemic hypertension." (PMID 35991314, 2022). "In addition for being aberrantly expressed in various cancers, levels of the Kruppel-like factor 5 (KLF5) are altered in all vascular smooth muscle cell (VSMC)-related diseases, such as atherosclerosis, restenosis after angioplasty, cardiac hypertrophy, and hypertension." (PMID 25988147, 2014). "Current research further proposes that miR-145 or miR-143 are part of the regulatory loop for KLF-4, KLF-5, MYOCD, and SRF; critical transcription factors the development of SMC phenotype, and lacking SMC correct differentiation could lead more easily to the development of atherosclerosis." (PMID 36836777, 2023).
atherosclerosis (continued). "Indeed, we found that cultured VSMCs from patients with atherosclerosis had decreased expression of the contractile markers calponin and α‐SMA, along with decreased expression of miR‐145 and MYOCD and increased expression in KLF5 compared with the VSMCs from patients without atherosclerosis." (PMID 26992033, 2016).
triple-negative breast carcinoma (25 papers, 2015 to 2025). An invasive breast carcinoma which is negative for expression of estrogen receptor (ER), progesterone receptor (PR), and human epidermal growth factor receptor 2 (HER2). "Previously, Metformin’s suppressive effect on triple negative breast cancer cells was linked to KLF5 transcription factor degradation through drop of cAMP and inactivation of PKA64." (PMID 29977599, 2018). "As an oncogenic epigenetic factor, BAP1 has been shown to facilitate tumor metastasis via stabilizing KLF5 in triple-negative breast cancer." (PMID 39817454, 2025). "KLF5 is highly expressed in triple-negative breast cancer and promotes cell proliferation, stemness, migration, and metastasis by regulating downstream target genes such as TNFAIP2 and XPO1." (PMID 40969325, 2025). "Meanwhile, we found that expression of KLF5 was significantly upregulated in triple negative breast cancer compared with luminal and HER2+ subtypes in TCGA." (PMID 35073911, 2022). "The Kruppel-like factor 5 (KLF5) transcription factor, highly expressed in high-grade, poorly differentiated and basal-like triple-negative breast cancer (TNBC), directly binds to the TNFAIP2 gene promoter and activates its transcription." (PMID 30754684, 2019). "Our previous work showed that KLF5 is highly expressed in ERa-PR-HER2 triple-negative breast cancer." (PMID 28032601, 2017). "For example, in one study, it was found that TEF3-1 interacted with KLF5 and suppressed p27 gene expression in triple negative breast cancers (TNBC) cell lines." (PMID 26885617, 2016). "Furthermore, YB-1 regulated KLF5 expression by inhibiting DACH1 transcriptional activation or stabilizing KLF5 mRNA construction, resulting in the progression of triple-negative breast cancer (TNBC)." (PMID 36750914, 2023). "Moreover, KLF5 was a dexamethasone (Dex)-induced gene that contributed to Dex-mediated drug chemoresistance in triple-negative breast cancer." (PMID 29898734, 2018). "Interestingly, a previous study revealed that mir-153 was involved in stemness maintenance of triple-negative breast cancer via reducing the expression of KLF5." (PMID 29221160, 2017). "PVT1 could also enhance the stability of Kruppel-like factor 5 (KLF5) and increase the expression of β-catenin, an important downstream effector of KLF5, to promote tumorigenesis in triple-negative breast cancer." (PMID 34527584, 2021). "Furthermore, we utilised the triple negative breast cancer cell line, CAL-51, which does not express ARID1A, complemented these cells with vectors expressing GFP or GFP-ARID1A WT and assessed the effect of KLF5 inhibition on their growth." (PMID 39779698, 2025).
lung carcinoma (22 papers, 2015 to 2025). "Taken together, our molecular analysis revealed a novel mechanism underlying the regulation of KLF5 protein expression and function in lung cancer, which involves arginine methylation by PRMT5 and proteasome‐mediated degradation." (PMID 37461162, 2023). "Abnormal expression or mutations of KLF5 can contribute to the development and progression of lung cancer." (PMID 37461162, 2023). "For example, the anoikis-associated genes KLF5 and FAIM2 are associated with the prognosis of colorectal and lung cancer, respectively, and silencing KLF5 and FAIM2 can significantly inhibit cancer cell anoikis resistance and proliferation." (PMID 36996495, 2023). "We next investigated whether the KLF5‐R41K mutation affects the expression of downstream targets of KLF5 and lung cancer cell proliferation." (PMID 37461162, 2023). "In addition, increased KLF5 expression was significantly associated with reduced OS in lung cancer." (PMID 39827156, 2025). "Interestingly, exogenous KLF5 only partially rescued lung cancer cell proliferation in PRMT5‐deficient cells, which may be due to additional roles of KLF5, such as transcriptional regulation of specific targets." (PMID 37461162, 2023). "Furthermore, KLF5 expression has been linked to a poor prognosis in lung cancer, and in vitro tests have shown that a decrease of KLF5 may overcome cisplatin resistance in lung cancer." (PMID 35345512, 2022). "Our findings indicate that KLF5 is highly associated with poor overall survival of patients with lung adenocarcinoma, suggesting that targeting KLF5-driven malignancy may provide an opportunity for developing lung cancer therapeutics." (PMID 35154481, 2022). "This pro-tumorigenic role of KLF5 is prominently observed in malignancies like lung cancer, colorectal cancer, liver cancer." (PMID 41583492, 2025). "Among the KLFs, the clear promoting effects on lung cancer were KLF5, KLF7, KLF8, and KLF15, as well as KLF4 and KLF6, which have dual functions." (PMID 38560274, 2024). "PRMT5 methylates the oncogenic factor Krüppel-like factor 5 (KLF5) to prevent its degradation, thereby promoting the maintenance and proliferation of lung cancer cells." (PMID 38418849, 2024). "As Fbw7 mediates KLF5 degradation via the proteasome, we explored the stability of KLF5 and the R41K mutant in lung cancer cells." (PMID 37461162, 2023). "KLF5 promotes the proliferation and metastasis of lung cancer cells by promoting the expression of STK24." (PMID 37181807, 2023). "We then assessed the tumour proliferation signature in lung cancer and found that both KLF5 and PRMT5 were positively correlated with tumour proliferation signature, suggesting a potential relationship between these two genes." (PMID 37461162, 2023). "In this study, we uncovered that PRMT5 functions as an arginine methyltransferase for KLF5 on arginine 41, leading to increased stability of the KLF5 protein in lung cancer." (PMID 37461162, 2023). "Above results promoted us to further illustrate the function of KLF5/STK24 axis in lung cancer cell function." (PMID 37181807, 2023). "Consistent with our previous results, we observed significantly higher expression of both PRMT5 and KLF5 in lung cancer cell lines compared to IMR90." (PMID 37461162, 2023). "Our findings not only illustrated the important role of STK24 in LUAD but also revealed a possible mechanism that STK24 was upregulated by KLF5 in lung cancer patients." (PMID 37181807, 2023). "Our results also demonstrated that PRMT5 was a critical epigenetic regulator for KLF5 to promote lung cancer cell growth." (PMID 37461162, 2023). "In the present study, we found that both PRMT5 and KLF5 were highly expressed and closely correlated in lung cancer cells." (PMID 37461162, 2023). "In this study, we found that PRMT5 stabilizes KLF5, further increasing its expression in lung cancer cells." (PMID 37461162, 2023).